NCAPD3 (non-SMC condensin II complex subunit D3)
Description:
Regulatory subunit of the condensin-2 complex, a complex which establishes mitotic chromosome architecture and is involved in physical rigidity of the chromatid axis. May promote the resolution of double-strand DNA catenanes (intertwines) between sister chromatids. Condensin-mediated compaction likely increases tension in catenated sister chromatids, providing directionality for type II topoisomerase-mediated strand exchanges toward chromatid decatenation. Specifically required for decatenation of centromeric ultrafine DNA bridges during anaphase. Early in neurogenesis, may play an essential role to ensure accurate mitotic chromosome condensation in neuron stem cells, ultimately affecting neuron pool and cortex size.
Synonyms: hCAP-D3; CAPD3; KIAA0056; CAP-D3; hHCP-6; FLJ42888; hcp-6; MCPH22
Tractability: PROTAC: ubiquitination databases record sites on it; its protein half-life has been measured.
Gene: Protein-coding gene on chromosome 11 (134,150,113 to 134,225,504, reverse strand). Ensembl gene ENSG00000151503.
Subcellular location: Nucleus
Subcellular location (Human Protein Atlas): Nucleoplasm
Pathways (Reactome):
Cell Cycle: Condensation of Prophase Chromosomes
Gene Ontology:
Molecular function: histone H4K20me1 reader activity; protein binding; histone binding
Biological process: mitotic chromosome condensation; chromatin organization
Cellular component: condensin complex; membrane; nucleoplasm; nucleus; pericentric heterochromatin; condensed chromosome, centromeric region; chromosome, centromeric region; nuclear lumen
Genetic constraint (gnomAD): Loss-of-function variants: 92 observed, 170.14 expected, observed/expected ratio (o/e) 0.54, 90% interval 0.46 to 0.64. The upper end of that interval is the gene's LOEUF score, 0.64, which puts it in group 2 of 6, group 1 being the genes least tolerant of losing a copy. Missense variants: 1,837 observed, 1,816.7 expected, observed/expected ratio (o/e) 1.01, 90% interval 0.97 to 1.05. Synonymous variants: 776 observed, 679.86 expected, observed/expected ratio (o/e) 1.14, 90% interval 1.08 to 1.21.
Homologues: Orthologues: chimpanzee NCAPD3 (99% identical), macaque NCAPD3 (96% identical), dog NCAPD3 (82% identical), rabbit NCAPD3 (82% identical), guinea pig NCAPD3 (78% identical), rat Ncapd3 (75% identical), mouse Ncapd3 (74% identical), pig NCAPD3 (73% identical), tropical clawed frog ncapd3 (57% identical), zebrafish ncapd3 (44% identical), Caenorhabditis elegans hcp-6 (21% identical), Drosophila melanogaster Cap-D3 (16% identical). Paralogues in human: NCAPD2 (15% identical).
Diseases named in the same sentence as NCAPD3 in open-access papers:
NCAPD3 is named in the same sentence as 38 diseases in open-access papers, as found by Europe PMC text mining. Sharing a sentence is not in itself a finding about the gene and the disease. The quoted sentences say what the papers report.
colorectal cancer (6 papers, 2022 to 2025). A primary or metastatic malignant neoplasm that affects the colon or rectum. "However, the clinical role, biological functions of NCAPD3 in cancers especially in colorectal cancer (CRC) and the underlying molecular mechanisms remain poorly elucidated." (PMID 35689245, 2022). "Functional experiments in vitro demonstrated that NCAPD3 exerts a pro-tumor effect in prostate cancer, gastric cancer, non-small cell lung cancer, and colorectal cancer." (PMID 40445456, 2025). "NCAPD3 also promoting the tumorigenesis of prostate cancer, gastric cancer, non-small cell lung cancer, and colorectal cancer tissues." (PMID 40445456, 2025). "NCAPD3 is high-expressed in prostate cancer, gastric cancer, non-small cell lung cancer, and colorectal cancer tissues." (PMID 40445456, 2025).
microcephaly (5 papers, 2019 to 2024). A congenital or acquired developmental disorder in which the circumference of the head is smaller than normal for the person's age and sex. "The clinical manifestations of this child are consistent with ASD and partially related to the phenotype of Type 22 primary microcephaly caused by mutations in the NCAPD3 gene." (PMID 38829782, 2024). "For example, biallelic mutations in NCAPD2, NCAPH, and NCAPD3 cause microcephaly." (PMID 36169232, 2022).
prostate carcinoma (5 papers, 2022 to 2025). A carcinoma that arises from epithelial cells of the prostate gland. "Much literature has reported that STAT3 has been implicated in promoting the oncogenesis and progression of prostate cancer, and we found that NCAPD3 not only promoted STAT3 expression but also regulated STAT3 phosphorylation." (PMID 39917394, 2025). "Abnormally expressed NCAPD3 in prostate cancer caused STAT3 to be highly expressed and bound to the promoters of JAK2 and EZH2 to promote their transcription, increasing the level of AKT phosphorylation, and accelerating tumor development." (PMID 39917394, 2025). "The results demonstrated that NCAPD3 promoted tumor growth in prostate cancer through down-regulating miR-30a-5p, which was associated with the regulation of STAT3, MYC, and EZH2." (PMID 38561330, 2024). "This differed from our result that NCAPD3 inhibited miR-30a-5p expression, which was regulated by AR signaling, indicating antitumor miR-30a might function in both androgen-dependent and independent states associated with prostate cancer progression." (PMID 38561330, 2024). "We have reported that NCAPD3 has higher expression in prostate cancer and is involved in androgen receptor‐promoted PCa progression." (PMID 39917394, 2025). "It is apparent that NCAPD3 significantly promoted prostate cancer cell viability and migratory capacity." (PMID 39917394, 2025). "This study aimed to figure out the detailed mechanisms by which NCAPD3 contributed to prostate cancer development." (PMID 39917394, 2025). "Our previous data also demonstrated that AR upregulated the expression of NCAPD3 in prostate cancer." (PMID 38561330, 2024). "To investigate the effect of NCAPD3 on prostate cancer development, we established stable NCAPD3-overexpression PC-3 cells (PC-3-Lv-NC3) and stable NCAPD3-knockdown 22Rv1 cells (22Rv1-Lv-shNC3)." (PMID 38561330, 2024). "In 2008, Lapointe pointed out that the postoperative recurrence rate is lower in prostate cancer patients with low postoperative NCAPD3 expression." (PMID 38711992, 2024). "In prostate cancer, NCAPD3 is identified as a new biomarker for subtype-1 tumors that improves prognostication." (PMID 35689245, 2022). "Our previous study finds that NCAPD3 is an androgen/androgen receptor (AR) axis-targeted gene and is involved in AR-promoted progression of prostate cancer." (PMID 35689245, 2022). "In this study, in vitro and in vivo experimental data confirmed that NCAPD3 was highly expressed in prostate cancer, which could activate AKT and promote PCa progression." (PMID 39917394, 2025). "Hence, NCAPD3 can be used as a prognostic predictor of prostate cancer after surgery." (PMID 38711992, 2024). "Taking this report together with our published literature, we proposed that NCAPD3 affected different stages of PCa through specific pathways, and these are still required to be confirmed by more high‐quality experiments, which could help to broaden the therapeutic strategies for prostate cancer." (PMID 39917394, 2025). "However, the underlying mechanism of NCAPD3 in prostate cancer (PCa) remains not completely clear." (PMID 38561330, 2024). "Our latest study also identified the interaction between NCAPD3 and E2F1 in prostate cancer which increased the binding of E2F1 to the promoter of EZH2." (PMID 35689245, 2022). "In summary, this work elucidates NCAPD3 inhibits miR-30a-5p through two pathways: increasing STAT3-MALAT1 to sponge miR-30a-5p and increasing MYC to directly inhibit miR-30a-5p transcription, which could serve as potential therapeutic targets for prostate cancer." (PMID 38561330, 2024).
colon adenocarcinoma (2 papers, 2019 to 2022). "Excitingly, our experiments using both the Seahorse and Oroboros instruments to measure oxygen consumption and test the function of ETC components revealed increased oxygen consumption and increased complex II function in NCAPD3-deficient HT-29 colon adenocarcinoma cells." (PMID 31653782, 2019).
gastric cancer (2 papers, 2024 to 2025). A primary or metastatic malignant neoplasm involving the stomach. "In vivo and in vitro experiments showed that NCAPD3 loss can significantly inhibit gastric cancer cell proliferation, invasion, and migration, and promote apoptosis." (PMID 38711992, 2024). "Association of NCAPD3 with clinicopathological characteristics from 67 gastric cancer patients." (PMID 38711992, 2024). "This is consistent with the result that inhibiting NCAPD3 expression promotes apoptosis in gastric cancer cells." (PMID 38711992, 2024). "Then the Effects of NCAPD3 knockdown on malignant biological behaviors of gastric cancer cells were detected by MTT, flow cytometry assays, Transwell invasion assays and scratch assays." (PMID 38711992, 2024). "In summary, this NCAPD3 research is expected to provide a new target for gastric cancer treatment and inspire new therapeutic strategies for in-depth basic research and new drug development in clinical practice for gastric cancer." (PMID 38711992, 2024). "Inhibiting NCAPD3 expression can attenuate the malignant biological behaviors of gastric cancer cells." (PMID 38711992, 2024). "In order to study the molecular mechanisms of malignant biological behavior in gastric cancer regulated by NCAPD3, GeneChip PrimeView human gene expression array was used to detect differentially expressed genes (DEGs) before and after NCAPD3 knockdown." (PMID 38711992, 2024). "NCAPD3 upregulation significantly promoted the malignant biological behaviors of gastric cancer cell, while NCAPD3 inhibition exerted a opposite effect." (PMID 38711992, 2024). "Representative IHC images posited that NCAPD3 protein was primarily expressed in the cytoplasm of gastric cancer cells." (PMID 38711992, 2024). "NCAPD3 promotes gastric cancer cell proliferation, invasion, and migration and inhibits apoptosis to accelerate gastric cancer progression." (PMID 38711992, 2024). "We then detected NCAPD3 protein expression in 67 pairs of gastric cancer tissues and paracancerous tissues with immunohistochemistry." (PMID 38711992, 2024). "The result showed that NCAPD3 expression level in gastric cancer tissues is significantly higher than paired paracancerous tissues, with a log2-fold change of 2.242 and FDR <0.01." (PMID 38711992, 2024). "Subsequently, in vitro and in vivo experiments were conducted on NCAPD3 to investigate the effects of NCAPD3 on gastric cancer cell proliferation, invasion, migration, and apoptosis through overexpression and knockout/knockdown experiments." (PMID 38711992, 2024). "NCAPD3 loss can directly inhibit CCND1 and ESR1 expression to downregulate the expression of downstream targets CDK6 and IRS1 and inhibit the proliferation of gastric cancer cells." (PMID 38711992, 2024). "In addition, NCAPD3 significantly affects many canonical pathways and immune and transcription factor gene sets in gastric cancer occurrence and progression." (PMID 38711992, 2024). "In order to further study the potential molecular mechanisms by which NCAPD3 regulates behavioral changes in gastric cancer cells, in this study, the human genome expression chip was used to detect differentially expressed genes and related signaling pathways before and after NCAPD3 knockdown." (PMID 38711992, 2024). "The results showed that NCAPD3 is significantly upregulated in gastric cancer tissues." (PMID 38711992, 2024). "Overall, this study shows that NCAPD3 may be a potential target for gastric cancer treatment." (PMID 38711992, 2024). "Moreover, NCAPD3 loss activates IRF7 and DDIT3 to regulate apoptosis in gastric cancer cells." (PMID 38711992, 2024). "Therefore, NCAPD3 downregulation may inhibit cholesterol synthesis, thereby affecting gastric cancer cell proliferation." (PMID 38711992, 2024).
gastric cancer (continued). "In order to further validate whether NCAPD3 directly targets CCND1, ESR1, and MYC to regulate gastric cancer cell proliferation, Co-IP experiments were conducted to examine if NCAPD3 directly interacts with CCND1, ESR1, and MYC." (PMID 38711992, 2024). "MGC803 gastric cancer cells that were transfected with the empty lentivirus vector (negative control) and NCAPD3-shRNA lentivirus vector were inoculated subcutaneously in nude mice, and tumorigenicity was observed." (PMID 38711992, 2024). "In summary, the NCAPD3 protein may target CCND1 or ESR1 to downregulate downstream factors such as CDK6 and IRSI to inhibit gastric cancer cell proliferation." (PMID 38711992, 2024). "The analysis results of Chi-square test revealed that The NCAPD3-positive expression rate in 67 gastric cancer patients was significantly higher than in paracancerous normal gastric mucosal tissues (p = 0.004)." (PMID 38711992, 2024). "Expression of NCAPD3 was identified to be correlated with invasion depth (p = 0.009), lymph node metastases (p = 0.029) and pathological TNM stage (p < 0.001) but not with other clinicopathological characteristics in patients with gastric cancer." (PMID 38711992, 2024). "To examine the function of NCAPD3 in gastric cancer, first, we measured NCAPD3 expression in four cancer-derived GC cell lines (AGS, BGC823, MGC803, and SGC7901) by RT-qPCR and found that the expressions of NCAPD3 mRNA in these four gastric cancer were all high-abundence." (PMID 38711992, 2024). "Therefore, NCAPD3 knockdown may inhibit CCND1, MYC, and ESR1 activity to downregulate CDK6 and IRS1 expression, thereby inhibiting the proliferation of gastric cancer cells." (PMID 38711992, 2024). "Therefore, NCAPD3 knockdown may activate IRF7, DDIT3, and HBEGF expression to promote gastric cancer cell apoptosis." (PMID 38711992, 2024). "Therefore, NCAPD3 knockdown may inhibit CCND1 and ESR1 expression to downregulate CDK6 and IRSI expression, thereby inhibiting the proliferation of gastric cancer cells." (PMID 38711992, 2024). "Therefore, NCAPD3 knockdown may inhibit CCND1, MYC, and ESR1 expression to downregulate CDK6 and IRSI expression, thereby inhibiting the proliferation of gastric cancer cells." (PMID 38711992, 2024). "However, there have been no studies on the correlation between NCAPD3 and gastric cancer." (PMID 38711992, 2024).
Primary microcephaly (2 papers, 2022 to 2025). Head circumference below 2 standard deviations below the mean for age and gender at birth. "In addition, also mutations in genes encoding condensin I and II complex members are associated with primary microcephaly, e.g., NCAPD2, NCAPH, NCAPG2 or NCAPD3, which showed altered expression levels in our data as well." (PMID 35099000, 2022).
ulcerative colitis (2 papers, 2017 to 2025). An inflammatory bowel disease involving the mucosal surface of the large intestine and rectum. "In addition, NCAPD3‐induced activation of IKK/NF‐κB pathway and secretion of proinflammatory cytokines TNF‐α/IL‐6 promote the development of ulcerative colitis." (PMID 39917394, 2025).
autosomal recessive primary microcephaly (1 paper, 2019). Autosomal recessive primary microcephaly (MCPH) is a rare genetically heterogeneous disorder of neurogenic brain development characterized by reduced head circumference at birth with no gross anomalies of brain architecture and variable degrees of intellectual impairment. "This is an intronic variant of the NCAPD3 gene (non-SMC condensin II complex subunit D3) and was found in compound heterozygous state in combination with the frameshift mutation NC_000011.9:g.134063952del in a patient with autosomal recessive primary microcephaly-22 (MCPH22)." (PMID 30744685, 2019).
benign prostatic hyperplasia (1 paper, 2024). A non-cancerous nodular enlargement of the prostate gland. "Compared to human prostate stromal WPMY1 cells and benign prostatic hyperplasia BPH1 cells, all tumor cell lines (PC-3, DU 145, 22Rv1 and LNCaP) significantly increased NCAPD3 expression." (PMID 38561330, 2024).
breast carcinoma (1 paper, 2024). "First, Ncapd3 (Ncapd3-203) is key alternative splicing gene, which was also highly expressed in breast cancer." (PMID 39944401, 2024). "Ncapd3 is highly expressed in breast cancer, and the protein levels of NCAPD3 and the mRNA expression of Ncapd3 were decreased in THSG group." (PMID 39944401, 2024). "THSG could inhibit the proliferation in T47D cells by NCAPD3 -dependent ferroptosis, which provided novel insights into targeted strategy for breast cancer." (PMID 39944401, 2024). "It is worth noting that NCAPD3 was highly expressed in breast cancer, and THSG inhibited the expression level of NCAPD3 in T47D cells." (PMID 39944401, 2024). "Non-SMC condensin II complex subunit D3 (NCAPD3) has recently been demonstrated as a crucial oncogenic factor, nevertheless, the biological role of NCAPD3 in the pathogenesis of breast cancer has not been elucidated." (PMID 39944401, 2024). "Nevertheless, there is no knowledge of NCAPD3 contribution to the development of breast cancer." (PMID 39944401, 2024).
cervical adenocarcinoma (1 paper, 2019). An adenocarcinoma arising from the cervical epithelium. "For example, target genes specific to cervical adenocarcinoma cells were most enriched for PANTHER molecular function term DNA binding, bending (e.g., HIST2H2BE, NCAPD3, and NUSAP1)." (PMID 31752429, 2019).
colorectal tumors (1 paper, 2022). "In addition, IHC analysis also showed that NCAPD3 knockout led to remarkably weaker staining of c-Myc, E2F1 and GLUT1, as well as a significant decrease of the proliferation rates of colorectal tumors in NCAPD3± mice, as evidenced by lower proportions of Ki-67 nuclear staining." (PMID 35689245, 2022).
developmental delay (1 paper, 2018). "This gene was previously found to be associated with Parkinson's disease and its paralog NCAPD3 is associated with developmental delay." (PMID 30148849, 2018).
liver cancer (1 paper, 2024). An epithelial or non-epithelial malignant neoplasm that arises from the liver. "Studies have shown that NCAPG, as a homo-family protein of NCAPD3, can affect the proliferation and apoptosis of liver cancer cells through the PI3K/AKT signaling pathway, which is comparable with what we discovered." (PMID 38566039, 2024).
lung carcinoma (1 paper, 2024). "Kaplan-Meier analysis revealed that higher NCAPD3 expression in lung cancer patients was associated with a worse clinical outcome compared to low expression (log-rank p = 0.0015)." (PMID 38566039, 2024). "Our results were in agreement with our observations in NSCLC specimens, indicating the expression of NCAPD3 was significant upregulated in lung cancer cell lines, especially in the A549 and SPCA-1." (PMID 38566039, 2024). "Additionally, we successfully established NCAPD3 knockdown lung cancer cell lines and performed in vitro functional assays to investigate the regulatory role of NCAPD3 on the biological behavior of NSCLC cells." (PMID 38566039, 2024). "Additionally, we conducted a Kaplan-Meier survival analysis of the 184 lung cancer patients according to their NCAPD3 expression levels to investigate whether NCAPD3 is a possible prognostic factor for lung cancer." (PMID 38566039, 2024).
lymph node metastasis (1 paper, 2024). "Furthermore, knockdown of NCAPD3 greatly inhibited the migratory and invasive capacity of NSCLC cells, which is consistent with the finding that lower NCAPD3 expression is correlated to a reduced risk of lymph node metastasis and a higher overall survival rate." (PMID 38566039, 2024).
MELAS (1 paper, 2019). "It will be interesting to determine whether MT-TL1 is rate limiting for the mitochondrial phenotypes observed in NCAPD3-depleted cells, and whether links exist between MELAS patients and NCAPD3 levels." (PMID 31653782, 2019).
metastatic tumors (1 paper, 2022). "Consistently, overexpression of NCAPD3 resulted in a stronger Ki67 staining in lung metastatic tumors in comparison to the control group." (PMID 35689245, 2022).